RN7SL831P (RNA, 7SL, cytoplasmic 831, pseudogene)
Gene: Miscellaneous RNA gene on chromosome 1 (96,583,209 to 96,583,527, forward strand). Ensembl gene ENSG00000241992.
Homologues: Orthologues: chimpanzee Metazoa_SRP (97% identical), macaque Metazoa_SRP (87% identical). Paralogues in human: RN7SL1 (76% identical), RN7SL2 (75% identical), RN7SL3 (75% identical), RN7SL712P (73% identical), RN7SL147P (73% identical), RN7SL493P (73% identical), RN7SL296P (72% identical), RN7SL122P (72% identical), RN7SL125P (72% identical), RN7SL804P (72% identical), RN7SL44P (72% identical), RN7SL15P (71% identical), and 698 more.